EGFR (epidermal growth factor receptor)
Diseases named in the same sentence as EGFR in open-access papers (continued):
Sharing a sentence is not in itself a finding about the gene and the disease.
colorectal cancer (continued). "Overexpressed decorin reduced the activity of multiple receptor tyrosine kinases (RTKs) including the epidermal growth factor receptor (EGFR), an important player in colorectal cancer (CRC) pathogenesis." (PMID 32824864, 2020). "CGP was done in addition to established first tier reflex molecular testing as per national guidelines (e.g., EGFR/ALK for non-small cell lung cancer (NSCLC) and extended-RAS for colorectal cancer)." (PMID 32375398, 2020). "miR-202 was shown to inhibit cell proliferation and invasion of colorectal cancer and bladder cancer by targeting UHRF1 and EGFR respectively." (PMID 33002044, 2020). "Monoclonal antibodies like cetuximab, targeting the epidermal growth factor receptor (EGFR), and bevacizumab, targeting the vascular endothelial growth factor (VEGF), are an integral part of treatment regimens for metastasized colorectal cancer." (PMID 33092032, 2020). "In 2008, it was approved as a first-line treatment for EGFR-positive and KRAS wild-type colorectal cancer." (PMID 33383632, 2020). "Cancer cells found in HNC, colorectal carcinoma, and non-small cell lung carcinoma (NSCLC) often acquire genetic amplification of EGFR, and EGFR-containing EVs are released from these cancer cells." (PMID 32150875, 2020). "Limited options of targeted therapy for colorectal cancer narrowly focus on blocking cancer-generic targets VEGFR and EGFR." (PMID 30754629, 2019). "In a 3D culture system of colorectal cancer cells, the phosphorylation of MET and RON was higher in cells with weaker response to EGFR-directed antibody cetuximab." (PMID 31557260, 2019). "For example, high copy numbers of ERBB2, TOP2A, CCND1, EGFR and MYC are observed in many colorectal cancers." (PMID 31009485, 2019). "A short hairpin RNA (shRNA) screen of human kinases and several kinase-related genes revealed that knockdown of epidermal growth factor receptor (EGFR) synergized with PLX4032, a BRAF inhibitor, in the suppression of BRAFV600E mutant colorectal cancers." (PMID 31640753, 2019). "Increased or sustained signaling of the epidermal growth factor receptor (EGFR) plays an integral role in the tumorigenesis of many cancer types, including colorectal cancer (CRC), making it a compelling drug target." (PMID 30650638, 2019). "Such tumors, when treated with monoclonal antibody targeting the epidermal growth factor receptor (EGFR), will eventually develop resistance to anti-EGFR therapy, a characteristic most prominent in colorectal cancer." (PMID 31247990, 2019). "EGFR and HER2 overexpression has been reported to play important roles in colorectal cancer (CRC) development and metastasis." (PMID 30858756, 2019). "It was also observed that intrinsic resistance to gefitinib, an EGFR-tyrosine kinase inhibitor, is positively correlated with nuclear PKM2 levels in colorectal cancer cells." (PMID 31120964, 2019). "In colorectal cancer, preclinical studies with BRAF inhibitors have reported adaptive feedback reactivation of MAPK signaling involving EGFR." (PMID 30636931, 2019). "Our work uncovers the role and deciphers the function of the EGFR-ERK-MYC axis as a repressor of HBD1 expression and contributes to the understanding of HBD1 suppression observed in colorectal cancer." (PMID 30575780, 2018). "Regarding to the observations above that OGN suppressed EGFR activity in HT29 and SW620 colorectal cancer cells, we aimed to identify which downstream pathways of EGFR will be inhibited after OGN over-expression." (PMID 29499765, 2018). "Both EGFR tyrosine kinase inhibitors and ligand-blocking antibodies have been approved for treatment of NSCLC, head and neck cancers and colorectal cancers." (PMID 30323890, 2018).
colorectal cancer (continued). "β-arrestin-1 is required for prostaglandin E2 (PGE2) induced transactivation of epidermal growth factor receptor (EGFR), Akt signaling and colorectal cancer cell motility in vitro and liver metastasis in vivo." (PMID 29954076, 2018). "EGFR has high prevalence in multiple solid tumor types, such as head and neck cancers, NSCLC and colorectal cancers, and is an attractive target for cancer therapy." (PMID 30323890, 2018). "HDAC3 directly regulates the expression of EGFR by binding to promoter sequences of EGFR, while HDAC inhibitors can reverse the expression of EGFR in colorectal cancer cells." (PMID 30583572, 2018). "COTI-2 alone is more effective than cetuximab and erlotinib, two epidermal growth factor receptor (EGFR) targeting agents, at inhibiting the proliferation of multiple human colorectal cancer cell lines." (PMID 29364966, 2018). "Cetuximab is a chimeric human/mouse mAb that binds to the extracellular domain of EGFR and is approved by the FDA for the treatment of colorectal cancer with KRAS WT status and HNSCC." (PMID 29552307, 2018). "We found that NDAT blocked ST6Gal1-induced sialylation of EGFR and consequent PI3K activation, which are essential for proliferation of cancer cells in both K-ras wild-type (wt) and K-ras mutant colorectal cancer cells." (PMID 30187356, 2018). "In particular, a higher activation of the EGFR-PDGFR-cKIT network, in addition to the PI3K/AKT pathway, has been demonstrated in liver metastasis compared to primary colorectal cancer tumors." (PMID 29491834, 2018). "In human colorectal carcinoma HCT116 cells, Gb4 enhanced activation of EGFR-induced MAPK/ERK signaling through direct interaction with EGFR." (PMID 29773994, 2018). "In this study, we first found decreased expression of the EGFR protein following RHBDD1 knockdown in HCT116 and RKO colorectal cancer cell lines." (PMID 28445956, 2017). "To establish in vitro correlates for EGFR-targeted therapy responses observed in CRC patients, we first measured the effect of Cetuximab on cell viability of seven colorectal cancer (CRC) cell lines." (PMID 28199979, 2017). "The median PFS was 19.6 months in pathological grade III-IV colorectal cancer patients with high EGFR expression, the median PFS in pathological grade III-IV colorectal cancer patients with low EGFR expression was 30.67 months (χ2=3.846, P=0.05)." (PMID 27888614, 2017). "Immunohistochemistry (IHC) results demonstrated both EGFR and VEGF positivity in excised colorectal cancer, and hematoxylin and eosin (H&E) staining revealed tumor cell infiltration." (PMID 28432289, 2017). "Following the initial finding that human sialidase NEU3 co-immunoprecipitates with EGFR in HeLa cells, it has been found that NEU3 is directly involved in EGFR desialylation in colorectal cancer, promoting receptor dimerization, and therefore EGFR activation." (PMID 29088281, 2017). "In this study, we analysed GCN variation of the EGFR, HER2, c-MYC, and MET genes in 334 colorectal cancer tissue samples using silver-enhanced in situ hybridization (SISH)." (PMID 28764718, 2017). "Currently, the treatment of colorectal cancer in the first line setting using targeted therapy is limited to anti-VEGF therapy (bevacizumab, aflibercept) or anti-EGFR therapy (cetuximab, panitumumab) in combination with an oxaliplatin based therapy." (PMID 28060954, 2017). "The epidermal growth factor receptor (EGFR)/RAS/RAF/MEK/MAPK pathway plays a crucial role in the carcinogenesis, invasion and metastasis of colorectal cancer (CRC)." (PMID 29383110, 2017). "Correlation between EGFR, AKT1, MYC, KRAS and SRC and, colorectal cancers separately or in combination with the other genes are studied and confirmed." (PMID 29511483, 2017). "In the course of time, combinations of fluoropyrimidines, with oxaliplatin and irinotecan, as well as the use of anti-EGFR and anti-VEGF targeted agents have improved survival of patients with metastasized colorectal cancer (mCRC) to about 2.5 years." (PMID 28695301, 2017).
colorectal cancer (continued). "In patients with colorectal cancer, mutant KRAS clones emerging during treatment with EGFR-specific antibodies declined during treatment breaks." (PMID 28716075, 2017). "Two mAbs (cetuximab and panitumumab) and two TKIs (gefitinib and erlotinib), as first-generation EGFR inhibitors, have been used for the treatment of NSCLC, pancreatic cancer, HNSCC, renal cancer, and colorectal cancer (CRC)." (PMID 28356156, 2017). "UDCA is cytoprotective against secondary BAs such as DCA and has been previously shown to be able to inhibit DCA-induced activation of the EGFR/Raf-1/ERK signaling pathway in HCT-116 cells and in an azoxymethane mouse model for colorectal cancer." (PMID 29241453, 2017). "The purpose of this study was to explore gene copy number (GCN) variation of EGFR, HER2, c-MYC, and MET in patients with primary colorectal cancer (CRC)." (PMID 28764718, 2017). "Literature was searched for randomized trials comparing anti-EGFR or anti-VEGF antibodies, paired with FOLFIRI or FOLFOX, as first-line therapy for advanced colorectal cancer." (PMID 29029527, 2017). "In colorectal carcinoma, BRAF amplification induced resistance to RAF/EGFR or RAF/MEK combinations through sustained MAPK pathway activity." (PMID 29312620, 2017). "pathological grade, TNM stage, EGFR and nm23 expression had statistical significance to the PFS of post-operative patients with colorectal carcinoma (P<0.05)." (PMID 27888614, 2017). "Current modalities for colorectal cancer include therapies that target the VEGF (bevacizumab) and EGFR (cetuximab) pathways." (PMID 27413734, 2016). "Indeed, activating mutations in exon 20 of PIK3CA (3% of all colorectal cancer) may predict clinical resistance to anti-EGFR monoclonal antibodies, but the correlation is not strong enough to be applied as a routine negative predictive marker." (PMID 27999270, 2016). "Additional evidences has also been suggesting that cytotoxic chemotherapy is more effective among patients with high EGFR expression than in those with low EGFR expression in non-small-cell lung cancer (NSCLC) and colorectal cancer (CRC), respectively." (PMID 27399694, 2016). "Epidermal growth factor receptor (EGFR) and its ligands amphiregulin (AREG) and epiregulin (EREG) play a central role in the development of colorectal cancer, but the prognostic values of AREG and EREG are controversial." (PMID 27344184, 2016). "EGF/EGFR axis triggered EMT in cholangiocarcinoma cells, and β-catenin targeted EMT to promote metastasis in colorectal cancer cells." (PMID 27050434, 2016). "Human HCT116 colorectal cancer cells were treated with 0-300 nM NW457 for 24 h or 48 h, respectively, and the expression levels of ephrin A2 (EPHA2) and epidermal growth factor receptor (EGFR) were measured by FACS surface staining." (PMID 27259245, 2016). "It is true that the benefit of cetuximab or panitumumab, two well-known EGFR mAb approved by FDA, is restricted to patients with KRAS wild-type colorectal cancer, and only this subset of patients should receive these agents." (PMID 26840022, 2016). "In phase 1 studies imgatuzumab demonstrated promising efficacy in heavily pretreated patients with advanced EGFR-positive solid tumors and KRAS-mutant EGFR-positive advanced colorectal cancer." (PMID 27602494, 2016). "Other key event in colorectal cancer initiation is the induction of COX-2, throughout EGFR pathway, that mediates the synthesis of prostaglandin E2, an agent strongly associated with colorectal cancer development, stem cell expansion and metastasis." (PMID 26801617, 2016).
colorectal cancer (continued). "In three different colorectal cancer cell lines (DLD1, HCT-116 and RKO), suppression of EGFR and PIK3CA through the enhanced expression of miR-134 or -370 led to a suppression of the key molecules of the PI3K/AKT/mTOR pathway." (PMID 27095166, 2016). "The dual tyrosine kinase inhibitor AEE788 and celecoxib were used to inhibit EGFR/VEGFR and COX-2, respectively, in colorectal cancer cells." (PMID 26107817, 2015). "Many anti-EGFR monoclonal antibodies have been approved by the FDA for clinical treatment of head and neck cancer and colorectal cancer." (PMID 25960704, 2015). "In summary, we demonstrated that stiffer substrates enhanced MMP-7 expression by generating a positive feedback loop involving EGFR, integrin-β1, integrin-α2, MRLC and YAP on stiffer substrates in colorectal cancer." (PMID 26344692, 2015). "The EGFR/HER2/KRAS/BRAF signaling pathway has been reported in pancreatic cancer and colorectal cancer other than in ovarian cancer." (PMID 26490766, 2015). "In cases of BRAFV600E-positive colorectal cancers, inhibition of BRAFV600E alone was ineffective, largely due to feedback activation of epidermal growth factor receptor (EGFR)." (PMID 26284586, 2015). "Sera from colorectal cancer (n = 67) and colon benign tumor patients (n = 5) were analyzed for the presence of auto-antibodies to ribosomal P proteins (P0/P1/P2), CEA, EGFR and ErbB2." (PMID 25889931, 2015). "Here we define the bioactivity of DbαEGFR-scTRAIL with regard to both EGFR inhibition and TRAIL receptor activation in 3D cultures of Caco-2 colorectal cancer cells, which express wild-type K-Ras." (PMID 25198428, 2014). "New approaches targeting epidermal growth factor receptor (EGFR) have clearly improved the clinical benefits in several solid tumors, including colorectal cancer (CRC)." (PMID 24714091, 2014). "TAMs can promote tumor cell growth and metastasis, and recent research has indicated that TAMs can stimulate colorectal cancer cell invasion by upregulating matrix metalloproteinase (MMP) expression and activating epidermal growth factor receptor (EGFR)." (PMID 24885636, 2014). "Our previous studies on the role of ARNO in colorectal cancer tissues have revealed a high correlation with pEGFR and pIGF-IR, suggesting that ARNO possibly enhances the activation and signaling of EGFR and IGF-IR." (PMID 24618737, 2014). "Gefitinib is effective against colorectal tumor cells that express high levels of EGFR, and there is ongoing clinical evaluation of the efficacy of gefitinib in combination with CPT-11, in the treatment of colorectal cancers." (PMID 24454732, 2014). "Consequently, it is essential to investigate whether the co-expression of other members of the HER family in the EGFR positive cancers may contribute to resistance, or a poor response to therapy with the anti-EGFR mAbs cetuximab and panitumumab in patients with colorectal cancer." (PMID 24609222, 2014). "Colorectal cancer (CRC) cells made to be resistant to GDC-0941 were discovered to secrete amphiregulin, which resulted in increased EGFR/MAPK signaling." (PMID 25053989, 2014). "The reported expression of EGFR ranges from 8 to 100%, HER-2 from 1% to 89%, HER-3 from 16 to 89%, and HER-4 from 11 to 81% in colorectal cancer patients." (PMID 24609222, 2014). "Analysis of expressed mutated surface genes revealed recurrent mutations in genes belonging to pathways known to be involved in colorectal cancer, including the WNT (LRP5 and FZD10), TGFβ (TGFBR3 and ACVR1B) and RTK-Ras (EGFR and ERBB3) signaling pathways." (PMID 25193853, 2014). "Treatment with HDAC inhibitor has been previously found to decrease EGFR mRNA and promoter activity by dissociation of transcription factor SP1 from the EGFR promoter around the transcription start site of EGFR gene in colorectal cancer cells." (PMID 24707474, 2014).
colorectal cancer (continued). "To select EGFR/IGF-sensitive cell lines, we performed MTT assay by culturing the colorectal cancer cell lines HT29, SW620, SW480, HCT116, and LOVO in 1% FBS with EGF or IGF." (PMID 24618737, 2014). "The epidermal growth factor receptor (EGFR)/RAS/RAF/MEK/MAPK pathway is an important pathway in the carcinogenesis, invasion and metastasis of colorectal cancers (CRCs)." (PMID 24330663, 2013). "The addition of targeted anticancer drugs against the epidermal growth factor receptor (EGFR), the monoclonal antibodies cetuximab and panitumumab, has further improved patient outcome in advanced stage colorectal cancer." (PMID 23391248, 2013). "In conclusion, to the best of our knowledge, we show for the first time that concomitant immunoexpression of EGFR and TATI/SPINK1 is an independent prognostic marker for favourable prognosis in colorectal cancer patients." (PMID 24204699, 2013). "In the present study we evaluated the relationship between EGFR and TATI expression and its possible prognostic value in colorectal cancer." (PMID 24204699, 2013). "Epidermal growth factor receptor (EGFR) activation plays a role in colorectal cancer (CRC) carcinogenesis, and anti-EGFR drugs are used in treatment of advanced CRC." (PMID 24204699, 2013). "We studied the prognostic value of immunohistochemical expression of EGFR and concomitant expression of EGFR and TATI/SPINK1 in a series of 619 colorectal cancer patients." (PMID 24204699, 2013). "The combined treatment of the IGF-1R kinase inhibitor, NVP-AFW541 or PQIP with the epidermal growth factor receptor (EGFR) inhibitor erlotinib or tarceva triggers apoptosis and inhibits growth of colorectal carcinoma cell lines." (PMID 24182354, 2013). "EGFR mutations were assessed by TaqMan Mutation Detection Assays (TMDA) based on castPCR technology in 64 tumor samples: a training set of 30 NSCLC and 6 colorectal carcinoma (CRC) samples and a validation set of 28 NSCLC cases." (PMID 24364033, 2013). "Extensive research on the EGFR molecule has revealed its oncogenic role, particularly in NSCLC and colorectal carcinoma." (PMID 23403410, 2013). "In colorectal cancer (CRC), the EGFR gene has been found to be over expressed in more than 80% of tumors and is significantly associated with TNM stage T3." (PMID 22026926, 2011). "However, the benefits of anti-EGFR monoclonal antibody treatment of advanced colorectal cancer may be limited to patients without KRAS mutations." (PMID 21407216, 2011). "To understand such signaling kinetics and tumor growth suppression in response to cetuximab administration, we used a colorectal cancer cell line, HT29, which expressed the highest EGFR level of 6 colorectal cancer cell lines tested." (PMID 21554739, 2011). "The chimeric anti-EGFR antibody, also known as Cetuximab, was approved by the FDA for the treatment of colorectal cancer and head and neck cancer in 2004." (PMID 21687663, 2011). "There is evidence that KRAS mutations are highly specific negative prognostic factors of response (de novo resistance) to EGFR-targeted therapy in both NSCLC and colorectal cancer." (PMID 21792199, 2011). "As in colorectal cancer, expression of CDX2, VEGF-A, and EGFR was observed in the majority of cases, but HER2/neu expression and loss of PTEN expression are rare oncogenic abnormalities in this cancer." (PMID 19935793, 2010). "Among patients with advanced colorectal cancer (CRC), a small subgroup seems to benefit from the epidermal growth factor receptor (EGFR) inhibitor, cetuximab." (PMID 19953097, 2010).